NPIPB12 (nuclear pore complex interacting protein family member B12)
Tractability: Antibody: UniProt predicts a signal peptide or a membrane-spanning region.
Gene: Protein-coding gene on chromosome 16 (29,483,534 to 29,508,595, reverse strand). Ensembl gene ENSG00000169203.
Subcellular location: Membrane
Subcellular location (Human Protein Atlas): Nucleoplasm
Gene Ontology:
Cellular component: membrane
Homologues: Paralogues in human: NPIPB5 (99% identical), NPIPB4 (99% identical), NPIPB13 (95% identical), NPIPB11 (93% identical), NPIPB3 (45% identical), NPIPB8 (36% identical), NPIPB9 (35% identical), NPIPB6 (34% identical), NPIPB2 (33% identical), NPIPB15 (32% identical), NPIPB7 (32% identical), NPIPA2 (30% identical), and 7 more.